RN7SL12P (RNA, 7SL, cytoplasmic 12, pseudogene)
Gene: Miscellaneous RNA gene on chromosome 11 (66,712,720 to 66,713,009, reverse strand). Ensembl gene ENSG00000239553.
Homologues: Orthologues: chimpanzee Metazoa_SRP (98% identical), macaque Metazoa_SRP (91% identical), rabbit Metazoa_SRP (65% identical). Paralogues in human: RN7SL1 (83% identical), RN7SL2 (83% identical), RN7SL126P (81% identical), RN7SL3 (81% identical), RN7SL278P (81% identical), RN7SL664P (80% identical), RN7SL45P (80% identical), RN7SL14P (80% identical), RN7SL333P (80% identical), RN7SL381P (80% identical), RN7SL47P (80% identical), RN7SL509P (80% identical), and 705 more.